MGAT3 (beta-1,4-mannosyl-glycoprotein 4-beta-N-acetylglucosaminyltransferase)
Description:
It is involved in the regulation of the biosynthesis and biological function of glycoprotein oligosaccharides. Catalyzes the addition of N-acetylglucosamine in beta 1-4 linkage to the beta-linked mannose of the trimannosyl core of N-linked sugar chains, called bisecting N-acetylglucosamine (GlcNAc). It is one of the most important enzymes involved in the regulation of the biosynthesis of glycoprotein oligosaccharides. The addition of this bisecting GlcNAc residue alters not only the composition, but also the conformation of the N-glycan. The introduction of the bisecting GlcNAc residue results in the suppression of further processing and elongation of N-glycans, precluding the formation of beta-1,6 GlcNAc branching, catalyzed by MGAT5 since it is unable to use the bisected oligosaccharide as a substrate. Addition of bisecting N-acetylglucosamine to CDH1/E-cadherin modulates CDH1 cell membrane location. Inhibits NeuAc-alpha-2,3-Gal-beta-1,4-GlcNAc-formation which modulates sialylation levels and plays a role in cell migration regulation. In brain, addition of bisecting N-acetylglucosamine to BACE1 blocks its lysosomal targeting in response to oxidative stress and further degradation which increases its location to early endosome and the APP cleavage (By similarity). Adds bisecting GlcNAc residue to complex-type N-linked-glycans attached on fragment crystallizable (Fc) of IgGs. Readily converts fucosylated and non-fucosylated core glycoforms with terminal GlcNAcs on both antennae. Prior galactosylation of GlcNAc on the alpha(1->3) Man branch prevents N-glycan bisection, whereas galactosylation of GlcNAc on the alpha(1->6) Man branch is permissive.
Synonyms: GNT-III; GNT3
Tractability: Small molecule: a high-quality ligand is known. Antibody: UniProt predicts a signal peptide or a membrane-spanning region. PROTAC: ubiquitination databases record sites on it; a small molecule that binds it is known.
Target class: Enzyme; Transferase
Chemical probes: PF-06471553 (high quality)
Gene: Protein-coding gene on chromosome 22 (39,447,127 to 39,492,194, forward strand). Ensembl gene ENSG00000128268.
Subcellular location: Golgi apparatus, Golgi stack membrane
Pathways (Reactome):
Metabolism of proteins: Reactions specific to the hybrid N-glycan synthesis pathway
Gene Ontology:
Molecular function: beta-1,4-mannosylglycoprotein 4-beta-N-acetylglucosaminyltransferase activity; protein binding; glycosyltransferase activity
Biological process: intracellular protein localization; regulation of cell migration; amyloid-beta metabolic process; cellular response to oxidative stress; cognition; N-acetylglucosamine metabolic process; negative regulation of lysosomal protein catabolic process; positive regulation of protein localization to early endosome; protein N-linked glycosylation
Cellular component: Golgi membrane; membrane; Golgi cisterna membrane
Genetic constraint (gnomAD): Loss-of-function variants: 10 observed, 28.22 expected, observed/expected ratio (o/e) 0.35, 90% interval 0.22 to 0.6. The upper end of that interval is the gene's LOEUF score, 0.6, which puts it in group 2 of 6, group 1 being the genes least tolerant of losing a copy. Missense variants: 557 observed, 755.34 expected, observed/expected ratio (o/e) 0.74, 90% interval 0.69 to 0.79. Synonymous variants: 397 observed, 346.72 expected, observed/expected ratio (o/e) 1.14, 90% interval 1.05 to 1.24.
Homologues: Orthologues: chimpanzee MGAT3 (99% identical), macaque MGAT3 (99% identical), mouse Mgat3 (93% identical), rat Mgat3 (93% identical), pig MGAT3 (92% identical), tropical clawed frog mgat3 (68% identical), zebrafish mgat3b (61% identical), zebrafish mgat3a (52% identical), Drosophila melanogaster Mgat3 (21% identical).
Diseases named in the same sentence as MGAT3 in open-access papers:
MGAT3 is named in the same sentence as 64 diseases in open-access papers, as found by Europe PMC text mining. Sharing a sentence is not in itself a finding about the gene and the disease. The quoted sentences say what the papers report.
breast cancer (15 papers, 2011 to 2025). A primary or metastatic malignant neoplasm involving the breast. "Furthermore, Pamela Stanley’s group revealed that GnT-III (Mgat3)-deficient mice showed increased tumor growth and metastasis in a polyoma middle T (PyMT)-induced breast cancer model." (PMID 27136596, 2016). "For example, mammary tumor growth and metastasis induced by the polyomavirus middle T (PyMT) oncogene are reduced in Mgat5−/− mice (knockout for the gene encoding MGAT5), whereas Mgat3−/− mice (knockout for the gene encoding MGAT3) exhibit an accelerated appearance of mammary tumors induced by PyMT." (PMID 26539643, 2016). "This study utilized bioinformatics analysis to explore the role of MGAT3, a key gene involved in the formation of the bisecting GlcNAc structure, in breast cancer (BC)." (PMID 40760673, 2025). "MGAT3 was also introduced into another breast cancer cell line BT549, and overexpression of MGAT3 resulted in decreased proliferation, migratory ability and clonal formation." (PMID 32612952, 2020). "Our data showed the decreased levels of bisecting GlcNAc and down-regulated expression of MGAT3 in breast cancer cells than normal epithelial cells." (PMID 32612952, 2020). "Relative to controls, mice that lack MGAT3 and bisecting GlcNAc display more rapid development of PyMT‐induced mammary tumours, greater tumour burden, and higher incidence of early metastasis to lung (Song, Aglipay, Bernstein, Goswami, & Stanley, 2010)." (PMID 33304474, 2020). "Our findings showed that bisecting GlcNAc structures retarded the EMT progression induced by hypoxia, which suggested the therapeutic potential of enhancing MGAT3 as a treatment for controlling breast cancer development." (PMID 29593568, 2018). "Downregulation of Mgat3 in the mouse model of PyMT-induced mammary carcinoma accelerates migratory properties of cancer cells promoting the metastases to the lung." (PMID 29502191, 2018). "Epigenetic activation of MGAT3 was also confirmed in basal-like breast cancers sharing similar molecular and genetic features with HGSOC." (PMID 27429195, 2016). "The breast cancer dataset was also analyzed by HumanMethylation450 BeadChip data in regards to DNA methylation and MGAT3 expression in matched tissue samples." (PMID 27429195, 2016). "We then addressed the correlation between probe methylation score and MGAT3 expression in four breast cancer types." (PMID 27429195, 2016). "In concordance with our results on cell lines as well as TCGA breast cancer dataset analysis, samples with DNA hypermethylation had generally lower levels of MGAT3 expression in the TCGA datasets." (PMID 27429195, 2016). "However, deregulation of MGAT3 (or GnT-III), as observed in breast cancer and melanoma, can inhibit the epithelial-mesenchymal transition (EMT) of cancer cells and thus suppress metastasis." (PMID 40096084, 2025). "Our study indicated that MGAT3 might be a potential therapeutic target of hypoxic region of breast cancer." (PMID 29593568, 2018). "Interestingly, an inverse correlation between DNA methylation of MGAT3 and gene expression was also observed in basal-like breast cancer." (PMID 27429195, 2016). "Interestingly, we observed significantly elevated MGAT3 expression (ANOVA p < 0.001) in basal-like cancers compared to all other breast cancer subtypes and similar MGAT3 expression levels as in HGSOC." (PMID 27429195, 2016). "Downregulation of the enzyme MGAT3 in mouse mammary tumours increases cell migration and metastasis but genetic background may modify this effect in human breast cancer cells." (PMID 27007155, 2016). "Since we observed a correlation between MGAT3 expression and DNA methylation in breast cancer datasets, we investigated whether this finding can be translated to other human cancers." (PMID 27429195, 2016). "In breast cancer, MGAT1, MGAT2 and MGAT3 were downregulated, but MGAT4A, MGAT4B, and MGAT5 were increased." (PMID 36185271, 2022).
breast cancer (continued). "Overall, our data demonstrate, for the first time, a direct relationship between DNA methylation around the TSS of MGAT3, MGAT3 gene expression and the presence of bisecting GlcNAc in HGSOC and basal-like breast cancer." (PMID 27429195, 2016). "To further investigate the role of bisecting GlcNAc in breast cancer, we compared the MGAT proximitome with differentially expressed proteins following MGAT3 overexpression, identifying six overlapping proteins in both datasets, which were undetectable by PHA-E enrichment." (PMID 39851531, 2025). "We overexpressed MGAT3 in breast cancer MDA-MB-231 cells, and overexpression of MGAT3 significantly enhanced the bisecting N-GlcNAc on EGFR and suppressed the EGFR/Erk signaling, which further resulted in the reduction of migratory ability, cell proliferation, and clonal formation." (PMID 32612952, 2020).
ovarian carcinoma (13 papers, 2014 to 2024). A malignant neoplasm originating from the surface ovarian epithelium. "Bisecting GlcNAc N‐glycan structures have been recently associated with survival in ovarian cancer and were found to result from an epigenetically regulated MGAT3 expression." (PMID 28853212, 2017). "Regarding N-glycans, bisecting GlcNAc has been identified as a hallmark of epithelial ovarian cancer and mannosyl β(1 → 4)-glycoprotein β(1 → 4)-N-acetylglucosaminyltransferase (MGAT3), the glycosyltransferase involved in its biosynthesis, showed a clear upregulation in ovarian cancer." (PMID 27242953, 2016). "Despite a recently described correlation of MGAT3 and bisecting GlcNAc in ovarian cancer cells, it remains unknown whether DNA methylation is causative for the presence of bisecting GlcNAc." (PMID 27429195, 2016). "We next expanded our analysis to investigate whether this strong association of DNA methylation, MGAT3 gene and bisecting GlcNAc expression can be translated also to non-ovarian cancer cell lines of which N-glycan profiles are present." (PMID 27429195, 2016). "Our previous study suggested a correlation between bisecting GlcNAc containing N-glycoproteins and MGAT3 expression, which might be linked to the methylation status of the MGAT3 promoter in ovarian cancer cell lines." (PMID 27429195, 2016). "The glycosylation -related gene MGAT3 expression is epigenetically regulated by DNA hypomethylation, leading to synthesis of the unique type N-glycans on ovarian cancer cell membrane proteins." (PMID 38911294, 2024). "Knockdown of MGAT3 reduced the growth of ovarian cancer in a mouse model, and the modification of Notch1 with bisecting GlcNAc was shown to cause lysosomal degradation of Notch1 and be involved in this cancer-suppressive phenotype." (PMID 31936666, 2020). "The regulatory impact of DNA methylation on MGAT3 gene expression was previously shown for several ovarian cancer cell lines, including the BG1 cell line." (PMID 31410472, 2019). "Bisecting GlcNAc is up-regulated in ovarian cancers, while treatment with 5-AZA of ovarian cancer cell lines induces MGAT3, bisecting GlcNAc expression, and changes in the pattern of glycosylation of secreted glycoproteins." (PMID 28481247, 2017). "Our previous findings have indicated that the relative ion intensities of bisecting GlcNAc-type bi-antennary N-glycans correlate with MGAT3 expression in ovarian cancer cells." (PMID 27429195, 2016). "For example, DNA hypomethylation of the MGAT3 promoter is involved in its upregulation in ovarian cancer cells." (PMID 27136596, 2016). "Trans-well migration assays indicated that MGAT3 behaves as a suppressor in ovarian cancer cell migration." (PMID 24516574, 2014). "Immunhistochemistry analysis of MGAT3 expression in ovarian cancer tissues also showed correlation of over-expression of MGAT3 with lower metastatic potential, which was in line with the result from ovarian cancer cell lines." (PMID 24516574, 2014). "Since SKOV3-ip cells are the highly metastatic derivatives of SKOV3 cells, these results suggested a potential role of MGAT3 and its catalysate, bisecting glycans, on ovarian cancer cell motility." (PMID 24516574, 2014). "We further assessed MGAT3 expression in 24 ovarian cancer tissues employing immunohistochemical analysis." (PMID 24516574, 2014). "While only 14.29% of high grade ovarian cancer, 76.47% of low grade ovarian cancer specimens displayed moderate to strong staining of MGAT3." (PMID 24516574, 2014). "The expression levels of MGAT3 displayed a decreasing pattern, going from low grade ovarian cancer to high grade ovarian cancer." (PMID 24516574, 2014). "Furthermore, we reveal that the glycosyltransferase MGAT3 is responsible for CD82 glycosylation in ovarian cancer cells." (PMID 32483464, 2020). "Interestingly, MGAT3 is significantly downregulated in ovarian cancer metastasis that contributes at least in part to provoke low glycosylation of CD82." (PMID 32483464, 2020).
ovarian carcinoma (continued). "Furthermore, in ovarian cancer, MGAT3 was epigenetically upregulated, and the high levels of MGAT3 are correlated with poor prognosis." (PMID 31936666, 2020). "Knockdown MGAT3 in the ovarian cancer cell lines using shRNA impaired the glycosylation of CD82." (PMID 32483464, 2020). "Metastatic ovarian cancers express reduced levels of MGAT3 which in turn may result in impaired CD82 glycosylation." (PMID 32483464, 2020). "Mechanisms underlying MGAT3/ bisecting GlcNAc expression in cancer have not been analyzed in detail, especially in ovarian cancer." (PMID 27429195, 2016). "Next, we addressed the question whether the regulation of MGAT3 expression by DNA methylation of the TSS is a common feature of ovarian cancer cells." (PMID 27429195, 2016). "In regards to ovarian cancer, the presence of this glycan motif was described in membrane and secreted glycoproteins from serous ovarian cancer specimens and MGAT3 expression was shown to be elevated in ovarian cancer cell lines and tissue when compared to normal counterparts." (PMID 27429195, 2016). "Since ovarian cancer is the gynecological cancer with the poorest prognosis and displayed highest MGAT3 expression, we investigated whether MGAT3 expression correlates with survival in all TCGA PANCAN12 cancer samples and in particular, HGSOC." (PMID 27429195, 2016). "In addition, GnT-III (MGAT3) transcripts or its product bisecting GlcNAc are aberrantly upregulated in some other cancer cells including ovarian cancer and leukemia, suggesting that bisecting GlcNAc plays certain roles in cancer development and progression." (PMID 27136596, 2016). "In this study, we investigated whether DNA methylation of MGAT3 gene in ovarian cancer can lead to the presence of corresponding N-glycosidic products bearing bisecting GlcNAc and how MGAT3 expression impacts on cancer patient survival." (PMID 27429195, 2016). "In the case of ovarian cancer, relationship between bisecting glycan modification as well as MGAT3 and metastatic potential remains unclear." (PMID 24516574, 2014). "Immunohistochemical analysis indicated that lower MGAT3 expression correlated to ovarian cancers with higher malignant potential, which was in accordance with the results obtained from the SKOV3 cell line and its high metastatic derivative, SKOV3-ip cell lines." (PMID 24516574, 2014). "We further uncovered a previously undescribed mechanism that MGAT3 is a critical glycosyltransferase, which promotes CD82 glycosylation in ovarian cancer cells." (PMID 32483464, 2020). "We have previously shown that the product of GnT-III (encoded by the MGAT3 gene), bisecting GlcNAc, is present on ovarian cancer cells but is absent on human ovarian surface epithelial cells." (PMID 27429195, 2016). "Notably, decreased MGAT3 expression and increased MGAT5 expression may be concurrent phenomenon that both contribute to increasedβ1,6 GlcNAc branching in highly metastatic ovarian cancer." (PMID 24516574, 2014).
neuroblastoma (10 papers, 2009 to 2026). Neuroblastoma (NB) is the most common solid, extracranial childhood tumor. "Our previous studies showed that the parental (NB_1) and N-glycan mutant (NB_1(-Mgat1), NB_1(-Mgat2), and NB_1(-Mgat3)) Neuroblastoma (NB) cell lines have compromised N-acetylglucosaminyltransferase activities: GnT-I, GnT-II, or GnT-III." (PMID 39736999, 2023).
hepatoma (9 papers, 2012 to 2025). "In hepatocellular carcinoma cells, HGF-induced EMT was associated with decreased expression of MGAT3 and increased MGAT5 expression." (PMID 34356834, 2021). "In summary, our findings identify Runx2 as a transcriptional activator of miR-23a and demonstrate that as an oncogene, miR-23a may promote lymphatic metastasis by targeting Mgat3, which regulates the branching pattern of N-glycans on the mouse hepatoma cell surface." (PMID 29743543, 2018). "In hepatocellular carcinoma cells, EMT induced by HGF reduced the expression of MGAT3 but increased that of MGAT5, FUT8 and B3GALT5." (PMID 34356834, 2021). "Meta-analysis of the MGAT3 promoter methylation revealed hypomethylation in hepatocellular carcinoma (HCC) compared to adjacent non-tumor tissue." (PMID 27073020, 2016).
melanoma (8 papers, 2012 to 2025). A malignant, usually aggressive tumor composed of atypical, neoplastic melanocytes. "Overexpression of GnT-III in highly metastatic melanoma cells was associated with reduced metastasis potential, and MGAT3-transfected melanoma cell performed significantly suppressed lung metastasis, which were consistent with our data." (PMID 29593568, 2018). "It has been shown that overexpression of GnT-III (MGAT3) in highly metastatic mouse melanoma B16 cells led to a decreased synthesis of β1,6-branching through the competition for substrate between GnT-V and the overexpressed GnT-III." (PMID 34440905, 2021). "Transfection of MGAT3 in B16 melanoma cells resulted in suppressed tumor invasion and lung metastasis." (PMID 24516574, 2014). "In melanoma, MGAT3 upregulation, which in turn increased bisecting GlcNAc modification of E-cadherin, led to an enhancement of E-cadherin-mediated cell-cell interactions owing to prolonged turnover of E-cadherin on the cell surface." (PMID 24516574, 2014).
Alzheimer disease (7 papers, 2016 to 2024). A progressive, neurodegenerative disease characterized by loss of function and death of nerve cells in several areas of the brain leading to loss of cognitive function such as memory and language. "Based on a previous report which showed MGAT3 mRNA to be upregulated in brain tissue of patients with Alzheimer’s disease (AD), we investigated the pathological role of bisecting GlcNAc in the brain in the context of AD using Mgat3-deficient mice." (PMID 34445285, 2021). "Preliminary data illustrate MGAT3 mRNA as a potential biomarker of response to vitamin D therapy in Alzheimer’s disease, hinting at its translational potential; however, these findings remain to be independently validated." (PMID 27579147, 2016). "Dr. Endo’s group found upregulation of MGAT3 mRNA level in Alzheimer’s disease (AD) patient brains." (PMID 31936666, 2020).
cervical carcinoma (5 papers, 2012 to 2024). A carcinoma arising from either the exocervical squamous epithelium or the endocervical glandular epithelium. "Therefore, we analyzed MGAT3 expression in the cervical cancer cell line, HeLa and the leukemia cell line, K562, showing differential MGAT3 expression." (PMID 27429195, 2016).
liver cancer (4 papers, 2014 to 2023). An epithelial or non-epithelial malignant neoplasm that arises from the liver. "miR-23a may affect the formation of N-glycochain branches on the cell surface through glucose transferase MGAT3, thereby increasing the metastasis potential of liver cancer, which provides a new idea for the mechanism of action of MGAT3 in tumor metastasis." (PMID 35410157, 2022). "Future studies should investigate the exact roles of MGAT3 and MGAT5 in the context of each type of liver cancer." (PMID 36890858, 2023).